MDH1B (malate dehydrogenase 1B)
Synonyms: FLJ25341; RP11-95H11
Tractability: No criterion of Open Targets' tractability assessment is met for any kind of drug.
Gene: Protein-coding gene on chromosome 2 (206,737,763 to 206,765,328, reverse strand). Ensembl gene ENSG00000138400.
Gene Ontology:
Molecular function: L-malate dehydrogenase (NAD+) activity; catalytic activity; malate dehydrogenase activity; oxidoreductase activity, acting on the CH-OH group of donors, NAD or NADP as acceptor
Biological process: malate metabolic process; NAD+ metabolic process; oxaloacetate metabolic process; tricarboxylic acid cycle
Genetic constraint (gnomAD): Loss-of-function variants: 43 observed, 49.29 expected, observed/expected ratio (o/e) 0.87, 90% interval 0.68 to 1.12. The upper end of that interval is the gene's LOEUF score, 1.12, which puts it in group 4 of 6, group 1 being the genes least tolerant of losing a copy. Missense variants: 486 observed, 551.23 expected, observed/expected ratio (o/e) 0.88, 90% interval 0.82 to 0.95. Synonymous variants: 198 observed, 195.46 expected, observed/expected ratio (o/e) 1.01, 90% interval 0.9 to 1.14.
Homologues: Orthologues: chimpanzee MDH1B (98% identical), macaque MDH1B (96% identical), pig MDH1B (78% identical), rabbit MDH1B (76% identical), dog MDH1B (73% identical), mouse Mdh1b (68% identical), rat Mdh1b (67% identical), guinea pig MDH1B (64% identical), tropical clawed frog mdh1b (45% identical), zebrafish mdh1b (37% identical), Caenorhabditis elegans mdh-1 (17% identical), Drosophila melanogaster Mdh1 (17% identical). Paralogues in human: MDH1 (18% identical).
Diseases named in the same sentence as MDH1B in open-access papers:
MDH1B is named in the same sentence as 4 diseases in open-access papers, as found by Europe PMC text mining. Sharing a sentence is not in itself a finding about the gene and the disease. The quoted sentences say what the papers report.
cancer (1 paper, 2022). A tumor composed of atypical neoplastic, often pleomorphic cells that invade other tissues. "Interestingly, many mitochondria-associated ELIdn genes were downregulated in fibroblasts with metastatic transition of cancer, including COX10, MSTO1, CPT2, and MDH1B." (PMID 35565326, 2022).
MDH1B also shares sentences with these, for which no sentence is quoted: cervical cancer (1 paper); lung carcinoma (1); tumor (1).